EGFR (epidermal growth factor receptor)
Diseases named in the same sentence as EGFR in open-access papers (continued):
Sharing a sentence is not in itself a finding about the gene and the disease.
glioma (continued). "Chromosome 7, with frequent copy number gains in all four cancers, harbors several key oncogenes such as EGFR, CDK6, and MET in glioma; KMT2C and PMS2 in medulloblastoma; BRAF, RAC1, and TRRAP in melanoma." (PMID 41537310, 2026). "The CPGs most frequently affected by GVs were ATM in 6/206 (2.9%) families, BRCA2 in 5/206 (2.4%) families (identified in approaches 1 and 2), GBA1 in 4/206 (1.9%) families as well as EGFR, GJB2, and SDHA in 3/206 (1.5%) families each of the glioma cohort." (PMID 41546701, 2026). "Conclusions: the EGFR-targeted TP-CTX-Lip significantly enhances the tumor selectivity and safety of TP, providing a promising strategy for targeted glioma therapy." (PMID 42198406, 2026). "In vitro release kinetics were evaluated in phosphate buffer (pH 7.4), and cytotoxicity was assessed in high-EGFR (U87-MG) and low-EGFR (SW1088) glioma cells." (PMID 42198406, 2026). "We observed frequent ERK pathway reactivation in human glioma specimens following BRAF inhibitors, most commonly through EGFR and PDGFRβ activation." (PMID 40900823, 2025). "In conclusion, our study proposes an AURKA-mediated EGFR/B7-H3 regulatory mechanism in glioma cells and highlights the importance of AURKA in enhancing B7-H3–targeting immunotherapy in glioma mouse models." (PMID 39928563, 2025). "EGFRvIII, EGFR, and HER2 are more frequently expressed in adult gliomas, while IL13Rα2, B7-H3, and GD2 appear to be suitable candidates for both adult and pediatric CNS tumors." (PMID 40895575, 2025). "For instance, high expression of POLR2J4 has been reported to be associated with poor prognosis in various malignancies, while SNHG16 promotes glioma tumorigenesis via activation of the PI3K/AKT pathway and the miR-373/EGFR axis." (PMID 40661083, 2025). "Cross-referencing this list with our in-house RNA-Seq dataset shows several HDACi resistance genes that are expressed at higher baseline levels in our IDHwt glioma cells, including EMP1, WWTR1, EGFR, and AGRN." (PMID 41066183, 2025). "The expressions of essential proteins for glioma progression, CD73, PD-L1, and EGFR in U251MG cells were also evaluated." (PMID 40191718, 2025). "Activation of P2X7R and TGFβ signalling in glioma stem cells has been shown to promote EMT, while in one study (C6 cell line), inhibition of P2X7R paradoxically increased EGFR activity and angiogenesis." (PMID 41374950, 2025). "Similar to adult‐type gliomas overall, we have observed that the influence of the TERT promoter on prognosis remains consistent across different EGFR statuses." (PMID 39804195, 2025). "SUV39H1 expression was positively correlated with the classic-like glioma subtype and markers such as NES and EGFR, with a lower correlation with mesenchymal-like markers like CD44 and CHI3L1." (PMID 40059829, 2025). "Our findings demonstrate that USP25 promotes glioma proliferation by stabilizing METTL3 in the cytoplasm, thereby enhancing EGFR translation." (PMID 41321637, 2025). "Recently, anti-EGFR therapies have been employed in the treatment of both GBM and low-grade gliomas." (PMID 40598793, 2025). "In glioma stem-like cells, FAK inhibition enhances sensitivity to EGFR inhibitors via β1-integrin/FAK/EGFR signaling." (PMID 41487565, 2025). "When employing the TCGA-UCI glioma grading dataset, the most discriminative and significant three features (63.6% ACC) are EGFR, FAT4, and BCOR." (PMID 40362575, 2025). "Nevertheless, to the best of our knowledge, this is the first study to investigate the relationship between MET- or FDG-PET and alterations in driver genes, including EGFR, PTEN, NF1, and CDKN2A/B in gliomas." (PMID 40786409, 2025).
glioma (continued). "In adult-type high-grade glioma, tumors with PDGFRA amplification and EGFR amplification demonstrate significantly elevated perfusion parameters, such as rCBV and relative cerebral blood flow." (PMID 40853542, 2025). "ELDR expression is significantly upregulated in GBM in relation to normal brain and low-grade gliomas (LGG) and is positively correlated with EGFR gene copy number and RNA transcript levels in GBM." (PMID 40678238, 2025). "circ-E-Cad RNA encodes the 254-amino-acid protein C-E-Cad, which binds to the EGFR CR2 domain through its unique 14-amino-acid carboxyl terminus and activates EGFR, thereby maintaining the tumorigenicity of glioma stem cells." (PMID 40034125, 2025). "For example, the circRNA-derived protein SPECC1-415AA regulates EGFR and restores sensitivity to TMZ in glioma cells." (PMID 40723354, 2025). "Traditionally, EGFR signals through a complex network of intermediates, including PI3K, Akt, MAPK1, and phospholipase C gamma (PLCG), to facilitate glioma development, which aligns with our observations." (PMID 39716938, 2025). "Epidermal growth factor receptor (EGFR) is one of the major targets for GBM treatment, and it is correlated with increasing glioma invasion." (PMID 41338458, 2025). "By negatively regulating EGFR, LRIG1 normally promotes apoptosis and inhibits proliferation and invasion of glioma cells as well as tumor angiogenesis." (PMID 41201961, 2025). "The Journal retracts the article “Differential Regulation of the EGFR/PI3K/AKT/PTEN Pathway between Low- and High-Grade Gliomas”, cited above." (PMID 40536529, 2025). "Network pharmacology and molecular docking analyses have identified EGFR and SRC as direct molecular targets of Kae in glioma therapy." (PMID 41009025, 2025). "Both EGFR and PTEN can act on the downstream PI3K−Akt pathway to promote glioma invasion and proliferation, which is consistent with previous results." (PMID 38348047, 2024). "We also quantified the protein expression levels of EGFR and PLK1 in the dissected glioma tissues by Western Blot." (PMID 38943253, 2024). "Overexpression of tyrosine kinase receptors (RTKs), namely EGFR, PDGFR, VEGFR, and FGFR, and their ligands is among the most frequent alterations in glioma tumorigenesis, leading to aberrant activation of their downstream molecular pathways." (PMID 39684714, 2024). "GLIMMERS is an open-source tool to facilitate assessment of CNV markers related to classification and grading of gliomas, including 1p/19q, CDKN2A/B, EGFR, and +7/−10." (PMID 38736685, 2024). "The results indicated that AMT, AS3MT, EGFR, NICN1, and POLR3K exhibited significant sex differences in expression within glioma tissues." (PMID 39722126, 2024). "In glioma and melanoma, IGFBP2 facilitates the nuclear accumulation of EGFR, thereby activating STAT3." (PMID 38918360, 2024). "Gliomasphere line specific (EGFR) and cell cycle markers (MKI67, TOP2A) dominated clustering and we noted enrichment of glioma stem cell (PTPRZ1, SOX2) and astrocytic markers (GFAP, S100B) in GS025." (PMID 38856710, 2024). "We further show that this AS signature can be regulated by mutant EGFR or IDH1 and elucidate the functional mechanisms of AS events in genes CERS5 and MPZL1 in promoting glioma malignancy." (PMID 38662454, 2024). "Silencing of cZNF292, circ‐DICER1, and circ_002136 downregulated glioma tube formation through angiogenesis corresponding genes consisting of EGFR, VEGFRs, SOX13, and ZIC4 in human gliomas." (PMID 37953502, 2024).
glioma (continued). "In 2013, the study of Jingwen Zhang revealed that tissue transglutaminase (TTG) blocks the EGFR ubiquitination catalyzed by c-CBL through the interaction with c-CBL, which enhances EGFR signaling and thus promotes the formation of glioma." (PMID 39130630, 2024). "Previous studies have identified biomarkers such as 1p/19q codeletion, isocitrate dehydrogenase, EGFR, and O6-methylguanine-DNA methyltransferase (MGMT) gene promoter methylation as indicators for gliomas." (PMID 38613802, 2024). "EGFR, BCAN, SOX2, PTN and CCN3 were found to be highly elevated in the glioma tumorous tissue with prominent fold change value, while other DE-ARGs, such as CLU, SCG3, showed no distinct expression alteration." (PMID 39033204, 2024). "Although EGFR alterations have been claimed to be mutually exclusive with FGFR fusions in gliomas, in the biopsy from initial diagnosis NGS revealed an EGFR amplification, that disappeared in the two subsequent biopsies." (PMID 39211518, 2024). "The combination of EGFR and autophagy regulation impairs cell migration and enhances the radiosensitivity of GBM, thereby improving treatment outcomes in patients with gliomas." (PMID 38304870, 2024). "EGFR and EGF have also been successfully used as targets to improve the PS delivery to glioma cells." (PMID 39201395, 2024). "An example is the “purple” module from the low-grade glioma (LGG) cohort of TCGA, which harbors the EGFR oncogene, a well-known driver of disease progression in glioma." (PMID 38685127, 2024). "EGFR, as an oncogenic gene, has been extensively investigated for its prognostic value in gliomas, especially IDH-wildtype gliomas." (PMID 38595969, 2024). "IHC glioma marker panel (SOX2, Tubulin, beta-3, EGFR, A2B5, and c-MET).FISH used to determine EGFR gene amplification in CTCs from known amplified cases." (PMID 38481938, 2024). "We have developed a prediction model for estimating the probability of 6-, 12-, and 18-month OS in recurrent glioma patients treated with BEV, which combines the information on adjuvant therapy, WHO 2021 grade, and EGFR alteration status." (PMID 38517553, 2024). "Subsequent construction of a protein-protein interaction (PPI) network, along with GO and KEGG enrichment analyses, highlighted EGFR and JUN as key prognostic targets for predicting five-year survival in glioma patients." (PMID 39850823, 2024). "Western blot analysis confirmed that DET downregulated EGFR and JUN in glioma cells, while molecular docking further verified the binding of DET to these targets." (PMID 39850823, 2024). "Knocking down LPP-AS2 resulted in decreased EGFR expression in glioma cells, while upregulation of LPP-AS2 led to escalated EGFR expression." (PMID 39553554, 2024).
glioma (continued). "The RNA sequencing analysis of 140 samples of the two cohorts ‘gliomas and BM revealed samples with gene rearrangements that involve NTRK3, FGFR3, ERG, EGFR, or MET genes in seven samples (5%)." (PMID 39087020, 2024). "We show that ANC@RNP/crEGFR‐PLK1 nanomedicine mediated efficient dual gene targeting of EGFR and PLK1 oncogenes in glioma cells with enhanced anti‐tumor effect versus single crRNA targeting of oncogenes." (PMID 38943253, 2024). "Studies have demonstrated the anti-glioma activity of EGFRvIII-specific CAR-T cells; however, patients with GBM often solely express wild-type EGFR, limiting therapeutic benefits." (PMID 38256021, 2024). "Our Cas12a RNP gene‐editing nanosystem (abbreviated as ANC@RNP) achieved up to 30–60% double knock‐out of EGFR and PLK1 oncogenes in glioma cell lines." (PMID 38943253, 2024). "VIP blocks the invasion of glioma cells exposed to hypoxia by regulating the expression of HIF and EGFR, which are involved in cell migration/invasion and angiogenesis." (PMID 39063232, 2024). "EGFR amplification and PTEN deletion have values in diagnosis, response to therapy and prognosis in molecular subgroups of gliomas." (PMID 39208202, 2024). "For example, dual-target CAR-T cells (e.g., targeting EGFR and IL-13Rα2, targeting EGFRvIII and wide-type EGFR protein) and triple-target CAR-T cells (e.g., targeting EphA2, IL-13Rα2, and EGFRvIII) have demonstrated promising potential in glioma therapy." (PMID 39506843, 2024). "We carried out immunohistochemical staining of the CD31, EGFR, and VEGFA proteins in primary glioma of tumor sites and hyperperfusion sites." (PMID 37534312, 2023). "The combination of EGFR signaling and IFN-γ response pathway can establish a more precise classification of gliomas." (PMID 37759950, 2023). "As an example, EGFR-KDD is present in human cancers, including glioma, with good response to the targeted therapies against EGFR." (PMID 37446288, 2023). "Currently, the gene therapy field is a hot topic in today’s study on glioma; researchers have discovered through gene sequencing technology that genes, including EGFR and ERT, can be used to diagnose potential glioma patients and determine the prognosis." (PMID 36672345, 2023). "Key findings in glioma patients in relation to m6A ‘readers’ include YTHDF2 overexpression, induced through the EGFR/SRC/ERK pathway to promote tumourigenesis, invasiveness, and cell proliferation independently associated with poor prognosis." (PMID 36831575, 2023). "To explore the prognostic effects of EGFR expression in molecular subtypes of LGG and GBM, we queried Glioma-BioDP." (PMID 37454191, 2023). "In vitro treatment of two glioma cell lines, LN229 and U251, with EGFR-CAR NK-cells infected with OV-IL15C significantly increased IFN-γ and TNF-α production." (PMID 38136398, 2023). "The expression of EGFRvIII in glioma cells leads to the expression of TGF-α and HB-EGF, resulting in EGFRvIII being involved in generating an autocrine loop with wild-type EGFR expression." (PMID 37446288, 2023). "In glioma, IGFBP2 forms a complex with the EGFR leading to EGFR accumulation inside the nucleus and induction of STAT3 transactivation." (PMID 37029430, 2023).
glioma (continued). "Consistent with previous studies that showed inhibition of RTK signaling in non-glioma cells upon EMP3 silencing, we observed higher EGF-induced EGFR degradation in our EMP3 KO cells." (PMID 37936247, 2023). "EGFR signaling activation induces the expression of multiple EMT markers and promotes the migration and proliferation of glioma." (PMID 37408388, 2023). "Nimotuzumab (Nimo) is a mAb that targets the epidermal growth factor receptor (EGFR) and is in late-stage clinical trials for high-grade glioma." (PMID 36980182, 2023). "Evidence from studies in EGFR-overexpressing U-87 MG glioma cells supported the antiproliferative effects of the targeted SLN, as well as the significance of surface anti-EGFR mAb for efficient drug delivery." (PMID 36678845, 2023). "Meanwhile, the amplification of EGFR and CDK4, and the deletion of PTEN and CDKNA2A/B were observed in the gliomas with high PVT1 expression." (PMID 37202742, 2023). "Concurrent inhibition of EGFR and JAK2/STAT3 was highly effective in a panel of molecularly heterogeneous glioma stem cells (GSC) and in orthotopic EGFRvIII GSC xenografts." (PMID 36900355, 2023). "In non-glioma cells, EMP3 facilitates the activation of receptor tyrosine kinase (RTK) signaling pathway components, including the epidermal growth factor receptor (EGFR)." (PMID 37936247, 2023). "Several growth factor receptors, including epidermal growth factor receptor (EGFR), platelet-derived growth factor receptor (PDRGF), and vascular endothelial growth factor receptor (VEGFR), are dysregulated in gliomas." (PMID 37895109, 2023). "Based on this relationship, EGFR-related and IFN-γ-related signatures were jointly used to divide the glioma patients." (PMID 37759950, 2023). "INHEG activation enhances rRNA 2’-O-methylation, thereby increasing the expression of oncogenic proteins including EGFR, IGF1R, CDK6 and PDGFRB in glioma cells." (PMID 37980347, 2023). "It has also been described that the EGF receptor is overexpressed in glioma cells and approximately 50% of GBM patients present EGFR amplification." (PMID 37284445, 2023). "TNC is a component of the glioma ECM that binds to integrin receptors, EGF receptor (EGFR), and SYNDECAN 4 (SDC4) and regulates angiogenesis, proliferation, and cell migration." (PMID 36707509, 2023). "We further demonstrated that the EGFR/AKT/GSK3β/β‐catenin axis played a role in IFI30‐promoted the EMT‐like phenotype, which is a well‐recognized mechanism in the diffuse infiltration of glioma cells." (PMID 37408388, 2023). "Epidermal growth factor receptor (EGFR) is a validated tumor marker overexpressed in various cancers such as squamous cell carcinoma (SSC) of the head and neck and gliomas." (PMID 35269611, 2022). "NT5DC2 can promote the tumorigenesis of glioma stem cell-like cells by inducing the expression of the FYN protooncogene and increase the proliferation of tumor cells in HCC by stabilizing the epidermal growth factor receptor." (PMID 36544763, 2022). "In summary, we clarified the oncogenic role of GBP2 in glioma and elucidated for the first time the GBP2/KIF22/EGFR pathway in glioma progression." (PMID 35436989, 2022).